LINC00665 (long independently transcribed non-coding RNA 665)
Diseases named in the same sentence as LINC00665 in open-access papers (continued):
Sharing a sentence is not in itself a finding about the gene and the disease.
colorectal cancer (6 papers, 2021 to 2022). A primary or metastatic malignant neoplasm that affects the colon or rectum. "They found significant upregulation of LINC00665 in colorectal cancer tissues compared to healthy control tissues." (PMID 35356290, 2022). "They conclude that LINC00665 promoted the progression of colorectal cancer by regulating the miR-9-5p/ATF1 axis." (PMID 35356290, 2022). "Experiments in vitro revealed that LINC00665 knockdown could inhibit the proliferation, migration, and invasion of colorectal cancer cells and induce apoptosis in colorectal cancer cells." (PMID 35356290, 2022). "Moreover, LINC00665 could promote the progression of colorectal cancer by regulating the miR-9-5p/ATF1 axis." (PMID 35251139, 2022). "In colorectal cancer, LINC00665 can interact with U2AF2, enhance the binding between U2AF2 and CTNNB1 mRNA, and increase the stability of CTNNB1 mRNA, thereby further activating the Wnt/β-catenin signaling pathway and stimulating the proliferation and invasion of colorectal cancer cells." (PMID 35563845, 2022).
lymph node metastasis (6 papers, 2021 to 2022). "The dysregulated expression of LINC00665 is closely associated with clinicopathological results (including larger tumor size, lymph node metastasis, distant metastasis, and advanced clinical stage), overall survival rate, and recurrence-free survival rate." (PMID 35356290, 2022). "Upregulated LINC00665 expression was correlated with the advanced T stage, lymph node metastasis, and the poor survival of PCa patients." (PMID 35664776, 2022). "High LINC00665 expression was associated with advanced tumor size, TNM stage, and lymph node metastasis." (PMID 35664776, 2022). "We found that high expression of LINC00665 was positively associated with a higher TNM stage, lymph node metastasis, and distant metastasis in CCA patients." (PMID 33436545, 2021). "The associations of LINC00665 expression level with Age, Serum PSA, Gleason score, Tumor size, T stage and Lymph node metastasis of PCa patients were further explored in this study." (PMID 34094920, 2021). "It was found that the expression of Linc00665 was positively correlated with lymph node metastasis." (PMID 33738251, 2021). "In addition, they concluded that the high expression of LINC00665 was positively correlated with higher TNM stage, lymph node metastasis, and distant metastasis in cholangiocarcinoma patients." (PMID 35356290, 2022). "Moreover, LINC00665 level was correlated to tumor size, FIGO stage and lymph node metastasis, rather than the age, histological grade, pathological subtype and CA125 level." (PMID 33613764, 2021).
osteosarcoma (6 papers, 2021 to 2024). A usually aggressive malignant bone-forming mesenchymal neoplasm, predominantly affecting adolescents and young adults. "LINC00665-drived polypeptide has tumor-suppressor features in osteosarcoma cells through repression of motility and proliferation by distracting the interaction of CREB1 and RPS6KA3." (PMID 38351332, 2024). "In osteosarcoma, LINC00665 can upregulate RAP1B by sponging miR-708-5p and miR-142-5p and promote tumor cell proliferation, migration, and invasion." (PMID 35563845, 2022). "Recent studies have found that the expression of Linc00665 was significantly upregulated in osteosarcoma samples than in normal samples, which was related to tumor size and tumor stage." (PMID 35356290, 2022). "In addition, LINC00665 competitively binds to miR-3619 and can also promote osteosarcoma progression." (PMID 35563845, 2022). "Moreover, the CCK8 assay, the wound-healing assay, and the transwell assay exhibited that the overexpression of LINC00665 promoted the proliferation, migration, and invasion of osteosarcoma cells." (PMID 35356290, 2022).
ovarian carcinoma (6 papers, 2020 to 2025). A malignant neoplasm originating from the surface ovarian epithelium. "For example, LINC00665 was highly expressed in ovarian cancer, and LINC00665 knockdown attenuated cell viability and favored patient prognostic survival by targeting miR-34a-5p." (PMID 38167456, 2024). "In ovarian cancer, the LINC00665/miR-34a-5p axis and LINC00665/miR-146a-5p axis promote cancer progression by upregulating E2F3 and CXCR4, respectively." (PMID 35563845, 2022). "As a consequence, FUT8-AS1, LINC00665 and LINC01535 were identified as key upstream lncRNAs of the ceRNA network in ovarian cancer." (PMID 33123295, 2020). "For instance, LINC00665 enhances FHDC1 expression in ovarian cancer by binding to and inhibiting miR-181a-5p, thus accelerating cancer development and presenting a potential new therapeutic target for ovarian cancer." (PMID 40999508, 2025).
endometrial cancer (5 papers, 2021 to 2022). Primary or metastatic malignant neoplasm involving the endometrium (mucous membrane that lines the endometrial cavity). "Loss of LINC00665 could repress endometrial carcinoma cell viability, induce cell apoptosis and block cell cycle in G1 phase." (PMID 33407473, 2021). "Moreover, given that LINC00665 up-regulation in endometrial carcinoma, we next examined whether loss of LINC00665 inhibited endometrial carcinoma cell proliferation." (PMID 33407473, 2021). "Mechanically, LINC00665 promoted the occurrence and progression of endometrial cancer by interacting with HMGA1." (PMID 35356290, 2022). "In endometrial cancer, LINC00665 can directly bind to the HMGA1 protein to promote tumor metastasis and invasion." (PMID 35563845, 2022). "Recent experiments have proved that LINC00665 also played a significant role in other cancers, including endometrial cancer, melanoma, cervical cancer, and thymoma." (PMID 35356290, 2022). "miR-214-3p is shown to modulate cell growth, metastasis, and apoptosis in HCC cells, endometrial cancer cells, and retinoblastoma cells by directly targeting certain genes linc00665, ATWIST1, BCB1, and XIAP." (PMID 36276270, 2022). "In endometrial carcinoma, LINC00665 was overexpressed in endometrial carcinoma tissues and cell lines." (PMID 35664776, 2022). "Expression of LINC00665 in clinical endometrial carcinoma tissues and cells was obviously up-regulated." (PMID 33407473, 2021). "This study demonstrated LINC00665 promoted endometrial carcinoma tumorigenesis and progression through interacting with HMGA1." (PMID 33407473, 2021). "In addition, we detected LINC00665 expression in commonly used endometrial cancer cell lines We found that LINC00665 was also increased in endometrial cancer cells (RL-95-2, Ishikawa, HEC-1B, KLE and HHUA cells) than in hESCs (P < 0.05)." (PMID 33407473, 2021). "Decrease of LINC00665 suppressed endometrial carcinoma tumorigenicity in vivo." (PMID 33407473, 2021). "These indicated LINC00665 was significantly increased in endometrial carcinoma." (PMID 33407473, 2021). "Therefore, LINC00665 can serve as an important oncogene in the progression of endometrial cancer." (PMID 33407473, 2021). "Thus, we suggested that LINC00665 may induce tumorigenesis by binding with HMGA1 in endometrial carcinoma." (PMID 33407473, 2021). "LINC00665 might promote endometrial carcinoma progression by positively modulating HMGA1." (PMID 33407473, 2021). "Mechanistically, LINC00665 co-immunoprecipitated with the HMGA1 protein and promoted the tumorigenicity of endometrial carcinoma in vitro and in vivo." (PMID 35664776, 2022). "Taken together, these data indicated a close interaction between LINC00665 and HMGA1 in endometrial cancer." (PMID 33407473, 2021). "Furthermore, mechanistic analysis indicated LINC00665 regulates the expression of HMGA1, thereby inducing endometrial cancer progression." (PMID 33407473, 2021). "The functions of LINC00665 in endometrial cancer have not been reported previously." (PMID 33407473, 2021). "Therefore, the data manifested that lack of LINC00665 suppressed endometrial carcinoma cell tumorigenesis in vivo." (PMID 33407473, 2021).
cholangiocarcinoma (4 papers, 2022 to 2023). A carcinoma that arises from the intrahepatic biliary tree (intrahepatic cholangiocarcinoma) or from the junction, or adjacent to the junction, of the right and left hepatic ducts (hilar cholangiocarcinoma). "Over-expression of LINC00665 has also been associated with poor prognosis and resistance of cholangiocarcinoma patients to chemotherapy." (PMID 36429005, 2022). "Next, they further checked the expression of LINC00665 in 100 pairs of cholangiocarcinoma samples and matched adjacent normal tissues." (PMID 35356290, 2022). "Abnormally upregulated LINC00665 was also involved in drug resistance in non-small cell lung cancer (gefitinib and cisplatin) and cholangiocarcinoma (gemcitabine)." (PMID 35563845, 2022). "In the Kaplan-Meier survival analysis, the overall survival time and recurrence-free survival time of cholangiocarcinoma patients with high LINC00665 expression were significantly shortened." (PMID 35356290, 2022). "They found that LINC00665 was significantly upregulated in gemcitabine-resistant cholangiocarcinoma cell lines." (PMID 35356290, 2022). "The results showed that LINC00665 was upregulated in cholangiocarcinoma patients, consistent with the previous results." (PMID 35356290, 2022). "LINC00665 can enhance the resistance of tumor cells to various chemotherapeutic drugs, including the resistance of non-small cell lung cancer cells to gefitinib and cisplatin, and the resistance of cholangiocarcinoma cells to gemcitabine." (PMID 35563845, 2022). "Furthermore, they reported that LINC00665 knockdown increased the cytotoxic activity of gemcitabine on cell apoptosis and growth, thereby weakening gemcitabine tolerance of resistant cholangiocarcinoma cells." (PMID 35356290, 2022). "Chemoresistant cholangiocarcinoma cells have exhibited higher EMT and stemness features, and LINC00665 knock-down has inhibited sphere formation, migratory potential, invasiveness, and levels of EMT and stemness marker proteins." (PMID 36429005, 2022). "In addition, knockdown of LINC00665 also downregulated Wnt/β-Catenin signaling and the expression of nuclear transcriptional regulator BCL9L in cholangiocarcinoma cells treated with gemcitabine." (PMID 35563845, 2022). "LINC00665 up regulation has been found in GEM-resistant cholangiocarcinoma (CCA) cells that was correlated with the prognosis and chemotherapy resistance of CCA patients." (PMID 37580768, 2023).
triple-negative breast carcinoma (4 papers, 2021 to 2023). An invasive breast carcinoma which is negative for expression of estrogen receptor (ER), progesterone receptor (PR), and human epidermal growth factor receptor 2 (HER2). "In triple-negative breast cancer, the protein CIP2A-BP encoded by LINC00665 can act as a protective factor to hinder cancer progression by inhibiting the PI3K/AKT/NFκB pathway." (PMID 35563845, 2022). "In addition, LINC00665 can also encode micropeptide CIP2A-BP, which is low expressed in tumor samples and reduces lung metastasis of triple-negative breast cancer in vivo." (PMID 35152838, 2022). "Notably, LINC00665 also encodes a micro-peptide CIP2A-BP that promotes triple-negative breast cancer progression." (PMID 35563845, 2022). "However, in triple-negative breast cancer, the expression of LINC00665 was significantly lower than in normal cells." (PMID 35563845, 2022).
acute myeloid leukemia (3 papers, 2021 to 2022). Acute myeloid leukemia (AML) is a group of neoplasms arising from precursor cells committed to the myeloid cell-line differentiation. "Through extracting the RNAs from acute myeloid leukemia (AML) or normal bone marrow tissues and cells, an RT-qPCR assay displayed that LINC00665 was upregulated in AML tissues and cell lines." (PMID 35664776, 2022). "LINC00665 has been shown to be up-regulated in acute myeloid leukemia (AML) cells parallel with the increase in expression of Dedicator Of Cytokinesis 1 (DOCK1) and decrease in expression of miR-4458." (PMID 36429005, 2022).
liver cancer (3 papers, 2022 to 2023). An epithelial or non-epithelial malignant neoplasm that arises from the liver. "LINC00665 can significantly promote liver cancer cell proliferation and tumorigenicity in vitro and in vivo, and the discovery of the NF-κB/LINC00665/PKR/NF-κB positive feedback loop provides a new way to understand the link between inflammation and cancer." (PMID 35563845, 2022).
melanoma (3 papers, 2022 to 2023). A malignant, usually aggressive tumor composed of atypical, neoplastic melanocytes. "Mechanically, they pointed that LINC00665 induced its oncogenic role via melanoma by upregulating VMA21 through sponging miR-224-5p." (PMID 35356290, 2022). "The expression of LINC00665 and AC018553.1 in both melanoma cell lines are higher than that in HaCaT." (PMID 37229449, 2023).
bladder cancer (2 papers, 2024). "Mechanistically, LINC00665 induces lymphatic metastasis via RAB27B-HGF-c-Myc loop between bladder cancer cells and CAFs." (PMID 39726782, 2024). "Blockade of EV-transmitted LINC00665 could abrogate lymphangiogenesis of bladder cancer in vivo." (PMID 39726782, 2024). "Subsequent research revealed that LINC00665 enhances RAB27B expression, thereby inducing a RAB27B-HGF-c-Myc positive feedback loop that promotes lymphangiogenesis and lymph node metastasis in bladder cancer." (PMID 39628486, 2024). "Furthermore, RAB27B-mediated EV secretion activates fibroblasts to CAF phenotype, which reciprocally induces LINC00665 overexpression to form a RAB27B-HGF-c-Myc positive feedback loop, promoting lymphangiogenesis and lymphatic metastasis of bladder cancer." (PMID 39726782, 2024).
breast invasive carcinoma (2 papers, 2019 to 2022). "What’s more, linc00665 was also hugely high expressed in lung squamous cell carcinoma, liver hepatocellular carcinoma, and breast invasive carcinoma (p < 0.0001), but low expressed in colon adenocarcinoma (p = 0.0006), compared with their adjacent normal tissues." (PMID 30692511, 2019).
lung fibrosis (2 papers, 2023 to 2025). "Our study is the first to reveal that the pathogenesis of CSE regulates LINC00665/XBP-1 in the process of pulmonary fibrosis." (PMID 38111802, 2023). "In summary, LINC00665 silencing can improve pulmonary fibrosis in mice and inhibit the fibrogenic effect of CSE on pulmonary fibroblasts." (PMID 38111802, 2023). "In summary, LINC00665 was highly expressed in BLM-induced lung tissues, and knockdown of LINC00665 alleviated BLM-induced pulmonary fibrosis." (PMID 38111802, 2023). "LINC00665 expression, was significantly upregulated in BLM-induced mouse lung fibrosis tissues, and LINC00665 knockdown inhibited fibrogenesis in BLM-induced lung fibrosis." (PMID 38111802, 2023). "LINC00665 was also found to be highly expressed in BLM-induced pulmonary fibrosis in mice, and LINC00665 silencing had an inhibitory effect on BLM-induced mouse pulmonary fibrosis." (PMID 38111802, 2023). "LINC00665 expression is upregulated in bleomycin-induced mouse lung fibrosis tissues, and inhibition of LINC00665 expression suppressed fibrogenesis in bleomycin-induced lung fibrosis." (PMID 41155727, 2025). "The inhibition of LINC00665 can inhibit the process of pulmonary fibrosis." (PMID 38111802, 2023). "In the next animal experiment, the expression of LINC00665 was markedly increased in the fibrotic lung tissues of the model group in a murine BLMinduced pulmonary fibrosis mouse model, and silencing LINC00665 antagonized the fibrogenic effect of BLM on the lung tissues of the mice." (PMID 38111802, 2023). "Next, in the mice model of pulmonary fibrosis, we confirmed that CSE positively regulates LINC00665/XBP-1 to participate in the lung fibroblast-to-myofibroblast transition and that LINC00665 regulates XBP-1 by negatively regulating miR-214-3p." (PMID 38111802, 2023).
non-small cell lung carcinoma (2 papers, 2022). A group of at least three distinct histological types of lung cancer, including non-small cell squamous cell carcinoma, adenocarcinoma, and large cell carcinoma. "LINC00665 is upregulated in non-small cell lung cancer and can activate the PI3K/AKT pathway by increasing the stability of EZH2, an important component of the initiation complex (PRC2), and mediates the expression of EGFR, thereby counteracting the effect of gefitinib." (PMID 35563845, 2022).
acute lymphoblastic leukemia (1 paper, 2022). Leukemia with an acute onset, characterized by the presence of lymphoblasts in the bone marrow and the peripheral blood. "LINC00665 was also found to be upregulated in T-cell acute lymphoblastic leukemia (T-ALL) and could promote T-ALL progression through the miR-101/PI3K/Akt pathway." (PMID 35664776, 2022).
cutaneous melanoma (1 paper, 2023). A primary melanoma arising from atypical melanocytes in the skin. "Similarly, silencing LINC00665 inhibits cutaneous melanoma progression via the miR-339-3p/TUBB axis." (PMID 37229449, 2023).
endometrial tumor (1 paper, 2021). "Moreover, a tumorigenesis assay proved that silence of LINC00665 restrained endometrial tumor growth." (PMID 33407473, 2021).
head and neck cancer (1 paper, 2024). A primary or metastatic malignant neoplasm affecting the head and neck. "The role of LINC00665 and its micro-peptide CIP2A-BP have yet to be studied in head and neck cancer." (PMID 39595048, 2024).
osteoarthritis (1 paper, 2024). A noninflammatory degenerative joint disease occurring chiefly in older persons, characterized by degeneration of the articular cartilage, hypertrophy of bone at the margins and changes in the synovial membrane. "Consistent with previous data, we verified that miR-214-3p was a downstream target of LINC00665 and its level was reduced in osteoarthritis tissues." (PMID 38167456, 2024). "To understand the mechanism by which LINC00665 regulates BMSCs to treat osteoarthritis, we performed in vitro cellular experiments." (PMID 38167456, 2024). "Therefore, LINC00665 may serve as a key target for osteoarthritis therapy and amelioration of joint injury according to LINC00665/miR-214-3p axis." (PMID 38167456, 2024). "Therefore, we speculated that LINC00665 knockdown may improve joint injury and alleviate the progression of osteoarthritis, while LINC00665 overexpression may aggravate the condition." (PMID 38167456, 2024). "The impact of LINC00665 on the proliferation and apoptosis of BMSCs was analyzed by transfection of LINC00665 overexpression, and the exploration of the molecular mechanism of LINC00665 in osteoarthritis provided a new direction for the rehabilitation of patients." (PMID 38167456, 2024). "Therefore, we hypothesized that LINC00665 may be a potential target for osteoarthritis." (PMID 38167456, 2024).
T-cell acute lymphoblastic leukemia (1 paper, 2022). Acute lymphoblastic leukemia of T-cell origin. "In addition, LINC00665 can compete with miR-101 to enhance the viability, migration, and invasion of cancer cells in T-cell acute lymphoblastic leukemia by activating the PI3K/Akt signaling pathway." (PMID 35563845, 2022).